NF2 (NF2, moesin-ezrin-radixin like (MERLIN) tumor suppressor)
Diseases named in the same sentence as NF2 in open-access papers (continued):
Sharing a sentence is not in itself a finding about the gene and the disease.
ependymoma (77 papers, 1999 to 2026). A WHO grade II, slow growing tumor of children and young adults, usually located intraventricularly. "Detection of NF2 mutations in ependymomas mandates genetic counseling and long-term follow-up for other manifestations of neurofibromatosis type 2." (PMID 41154124, 2025). "While spine ependymomas (including those with NF2 mutation) are, in general, regarded as good prognosis, MYCN-amplified spinal ependymomas in particular exhibit aggressive behavior, rapid progression, early metastases, and leptomeningeal dissemination." (PMID 41154124, 2025). "NF2-associated ependymomas were predominantly located in the cervical spinal cord (cervicomedullary: n = 2, cervical: n = 5, cervicothoracic: n = 2, thoracolumbar: n = 1)." (PMID 39713042, 2024). "The only well‐established risk factor for ependymomas is neurofibromatosis type 2 (NF2), which predisposes individuals to these tumors." (PMID 39777089, 2024). "Most data on the prevalence of NF2 mutations and 22q loss in spinal ependymal tumors were generated prior to the identification of distinct molecular ependymoma types and therefore show varying frequencies of these driver events." (PMID 38265489, 2024). "Based on the described meta-analysis, the current best estimate of germline predisposition in childhood ependymoma suggests that 3.4% (7/207) carry a causative pathogenic germline variant, mainly located in NF2 and NF1." (PMID 36008825, 2022). "Given their limited morbidity for the majority of patients, fewer therapeutic clinical trials have focused on NF2-associated ependymomas." (PMID 34885143, 2021). "The majority of ependymomas associated with NF2 appear to be asymptomatic and exhibit indolent growth." (PMID 34885143, 2021). "Trials of systemic therapeutic intervention in NF2-associated ependymomas are limited given their typical conservative management." (PMID 31161239, 2020). "On the other hand, the inclusion of ‘ependymoma' in the diagnostic criteria of NF2 would potentially improve positive predictive value." (PMID 31161239, 2020). "Given that most NF2-associated gliomas are in fact ependymomas, revision of the Manchester classification system to replace the term ‘glioma’ as a diagnostic criterion with ‘ependymoma’ has been suggested, though such changes have not yet been adopted." (PMID 31161239, 2020). "The most commonly observed recurrent somatic mutation in spinal ependymomas were indel and nonsense NF2 mutations in classic ependymomas (38.9%), consistent with several previous reports." (PMID 31822682, 2019). "Though recurrent somatic mutations in IMSCTs were rare, we identified NF2 mutations in 15.7% of tumors (ependymoma, N = 7; astrocytoma, N = 1), RP1 mutations in 5.9% of tumors (ependymoma, N = 3), and ESX1 mutations in 5.9% of tumors (ependymoma, N = 3)." (PMID 31822682, 2019). "In fact, ependymoma in the spinal cord is usually related to NF2 gene mutation (associated with frequent loss of Merlin, the protein encoded by the gene NF2), NFEL overexpression, and 9q gain reviewed in a past study." (PMID 30279357, 2018). "In this report, we leveraged Nf2−/− SC NPCs as an in vitro model system to define the growth control mechanism underlying spinal ependymoma pathogenesis relevant to the implementation of biologically-targeted treatments for these tumors." (PMID 24817309, 2014). "Taken together, our findings demonstrate that ErbB2 is a critical regulator of Nf2-deficient SC NPC survival and glial differentiation, and support further evaluation in preclinical and human clinical trials for NF2-associated and select sporadic ependymomas." (PMID 24817309, 2014). "There were no recurrent mutations in IEPs, despite all 8 being grade 3 (anaplastic) ependymomas and NF2 was the only recurrent mutation in SCEPs." (PMID 23592488, 2013). "Mutations in the NF2 gene are uncommon in sporadic ependymomas, and appear to be restricted to spinal tumours." (PMID 11953826, 2002).
ependymoma (continued). "In a study of 62 ependymomas, twelve showed allelic loss on 22q and six of them also had NF2 mutations." (PMID 11953826, 2002). "NF2‐associated ependymomas typically exhibit delayed growth and more benign behavior." (PMID 39777089, 2024). "Notably, a significant fraction of sporadic ependymomas with spinal localization have chromosome 22 aberrations and NF2 mutations." (PMID 39796693, 2024). "Also affecting the generalizability of the combined estimate is the fact that the two cohorts contributing 65% (112/173) of the total ependymoma sample size were limited to intracranial ependymoma, likely resulting in underreporting of NF2-associated cases." (PMID 36008825, 2022). "Both pLoF variants already known to cause ependymoma (in NF2 and NF1), were rediscovered." (PMID 36008825, 2022). "Combined with our findings of a cervicomedullary located ependymoma in a child with a pathogenic germline NF2 variant, there is mounting evidence that germline NF2-related ependymomas may be located intracranially, as well as intraspinally." (PMID 36008825, 2022). "Diagnosis of a glioma has traditionally been used as a diagnostic criterion for NF2; however, on clinicopathologic review nearly 80% of lesions characterized as NF2-associated gliomas are found to be spinal intramedullary or cauda equina ependymomas." (PMID 31161239, 2020). "We demonstrate that the Nf2 protein, merlin, negatively regulates spinal neural progenitor cell survival and glial differentiation in an ErbB2-dependent manner, and that NF2-associated spinal ependymomas exhibit increased ErbB2 activation." (PMID 24817309, 2014). "Molecular genetic studies on selected candidate genes revealed frequent NF2 gene mutations in intramedullary spinal ependymomas, while deletions of the CDKN2A gene were frequent in intracranial supratentorial ependymomas but rare in ependymomas from other locations." (PMID 19333441, 2009). "Moreover, the majority of ependymomas exhibiting NF2 loss occur in the spinal cord." (PMID 24817309, 2014). "A total of 14 patients (29%) died because of tumor or disease progression: AT/RT (6 cases), ependymomas (3 cases), NF-2 (2 cases), HGG, PNET and medulloblastoma (one case each)." (PMID 41515625, 2026). "Ependymal tumors are classified according to their molecular subgroup in conjunction with their compartmental occurrence, e.g., supratentorial ependymoma, ZFTA fusion positive, posterior fossa ependymoma group PFA, or spine anaplastic ependymoma (NF2 mutated)." (PMID 39897706, 2024). "A 25-year-old male with NF2 treated with selumetinib had a partial response in one spinal ependymoma and stable disease in other tumors at 3 months." (PMID 38058737, 2023). "Constrained gene analysis of children with molecularly confirmed ependymoma rediscovered the NF2 deletion detected in our cancer gene panel analysis." (PMID 36008825, 2022). "NF2, MEN1 syndrome, and Turcot syndrome are the best‐known genetic syndromes associated with ependymoma." (PMID 35689525, 2022). "Development of ependymomas, particularly in the cervical cord or cervicomedullary junction, is also a common finding in patients with NF2, and multiple ependymomas are found in over 50% of patients." (PMID 34885143, 2021). "Ependymomas are diagnosed in approximately 33–53% of individuals with NF2, most commonly involving the posterior fossa and cervicomedullary region of the spine." (PMID 31161239, 2020). "NF2 was sequenced in an additional 48 samples comprised of 32 intracranial, spinal ependymomas, 3 myxopapillary ependymomas and 2 spinal sub-ependymomas." (PMID 23592488, 2013). "This is the first reported case for using selumetinib in NF2 or ependymomas." (PMID 38058737, 2023). "However, pathogenic variants in the genes related to these familial syndromes (NF2, MEN1, APC, respectively) have only been observed in a few cases of sporadic ependymomas." (PMID 35689525, 2022).
ependymoma (continued). "Apart from NF2, none of the 14 constrained genes in which pLoF variants were detected have previously been linked with ependymoma." (PMID 36008825, 2022). "A causative 364 bp NF2 deletion (chr22:30067648–30068012; p.Met334_Leu374del [c.1000-167_1122 + 75del]) was detected in a young child diagnosed with a WHO grade 2 ependymoma (methylation class spinal ependymoma (SP-EPN)) located at the cervicomedullary junction." (PMID 36008825, 2022). "The diagnostic term ‘glioma’ may also be too broad and require further refinement, as diffuse gliomas are not strongly associated with the disease, and many lesions classified as such in NF2 patients are revealed to be ependymomas on review." (PMID 31161239, 2020). "We next reasoned that altered expression of chromosome 22 genes could help to identify potential candidate genes of ependymoma in addition to a NF2 gene." (PMID 25909290, 2015). "Whereas NF2 mutations are frequently associated to ependymoma such an association has never been described in Kabuki syndrome." (PMID 26341229, 2015). "From an earlier study in a family in which four cousins developed an ependymoma, we concluded that an ependymoma-susceptibility gene, which is not the NF2 gene in 22q12, might be located on chromosome 22." (PMID 10584875, 1999). "Moesin but not the related ERM family member merlin, the product of the neurofibromin 2 (NF2) gene, hereafter called NF2, has been shown to colocalize with NHERF1 in the microlumens of ependymoma." (PMID 29983887, 2018). "To investigate the composition of NHERF1 protein complexes in ependymoma, we screened the intracellular localization of the NHERF1 ligands moesin, NF2, PTEN, PDGFRα, EGFR, YAP1, β-catenin and PHLPP2 that have been functionally involved in primary brain tumors." (PMID 25775275, 2015). "NF2 IHC in normal ependymal lining and ependymomas showed only faint or no labeling of apical PM, respectively, suggesting that NF2, unlike moesin, is not a major ligand of NHERF1 in these polarized structures." (PMID 25775275, 2015).
neurofibromatosis type 1 (64 papers, 2009 to 2026). A clinically heterogeneous, neurocutaneous genetic disorder characterized by cafe-au-lait spots, iris Lisch nodules, axillary and inguinal freckling, and multiple neurofibromas. "Neurofibromatosis Type 2 related schwannomatosis (formerly known as neurofibromatosis type 2, NF2) is a tumor predisposition syndrome developed by inactivating the NF2 gene on chromosome 221." (PMID 40820211, 2025). "Multiple CALMs, a major clinical diagnostic criterion of neurofibromatosis type 1, have also been reported in NF2, with which it was initially confused." (PMID 35729665, 2022). "Neurofibromatosis type 2 (NF2) is a multiple tumor syndrome that results from loss-of-function mutations in the NF2 gene." (PMID 31312020, 2019). "Bilateral VSs are the hallmark of neurofibromatosis type 2 (NF2), an autosomal dominant disorder caused by inactivation or loss of both alleles of the NF2 gene." (PMID 29615643, 2018). "Neurofibromas have rarely been described in the literature in association with NF2 and are more commonly seen in neurofibromatosis type 1 (NF1)." (PMID 26709712, 2016). "Interestingly, NF2 is genetically unrelated to the more common neurofibromatosis type 1 (NF1) which is due to pathogenic variants of the tumor suppressor NF1 gene on chromosome 17." (PMID 33445724, 2021). "Cutaneous tumors may prompt further investigations that lead to the diagnosis of NF2, but skin manifestations in NF2 are much less obvious than those associated with neurofibromatosis type 1 (NF1)." (PMID 32591014, 2020). "Neurofibromatosis type 2 (NF2) is an autosomal-dominant tumor predisposition disorder caused by the inactivation of the NF2 tumor suppressor gene located on chromosome 22q12 and the functional loss of its protein product merlin (moesin-ezrin-radixin-like protein)." (PMID 31769423, 2019). "Tumours that warrant surgical therapy in the paediatric age group are mostly associated with neurofibromatosis type 1 (NF1) and less often neurofibromatosis type 2 (NF2)." (PMID 32506255, 2020). "As with the historical classification of NF1 and NF2 as a single diagnosis (von Recklinghausen’s disease), this view was significantly supported and propagated by Harvey Cushing in his 1917 review of tumors of this region." (PMID 31161239, 2020). "Neurofibromatosis type 1 (NF1) and type 2 (NF2) are hereditary, tumor predisposition syndromes that affect multiple systems." (PMID 32642740, 2020). "Cases of cardiac neurofibroma have rarely been associated with neurofibromatosis type 1; however, they have never been documented in patients with NF2." (PMID 40713130, 2025). "Although the mechanisms underlying their development are not entirely understood, these tumors are commonly associated with neurocutaneous disorders like neurofibromatosis type 1 (NF1) and type 2 (NF2)." (PMID 40895895, 2025). "Majority of GNs (97.6%) present sporadically, with the remainder associated with genetic syndromes such as neurofibromatosis type 1 (NF1) and type 2 (NF2), and multiple endocrine neoplasia type 2 (MEN 2)." (PMID 39691814, 2024). "There is scarce data on the quality of life of people with neurofibromatosis type 1 (NF1) and type 2 (NF2) in Canada." (PMID 32642740, 2020). "There are two major forms, designated neurofibromatosis type 1 (NF1) and neurofibromatosis type 2 (NF2), which are clinically and genetically distinct." (PMID 23049566, 2012). "It is clinically divided into several subtypes, with the 2 most common subtypes being neurofibromatosis type 1 (NF1) and NF2." (PMID 40153767, 2025). "They encompass a broad range of conditions, including neurofibromatosis type 1 (NF1), neurofibromatosis type 2 (NF2), tuberous sclerosis complex, Sturge–Weber syndrome, von Hippel–Lindau disease, and others." (PMID 40843672, 2025).
neurofibromatosis type 1 (continued). "Neurofibromatosis is an autosomal dominant inherited disorder and is classified as neurofibromatosis type 1 (NF1), which accounts for 96–97%, or neurofibromatosis type 2 (NF2), which accounts for 3–4% of cases." (PMID 34581917, 2021). "GEP NET have occasionally been described in association with neurofibromatosis type 1 (NF1), whereas an association with NF2 has never been reported." (PMID 24961548, 2014). "Neurofibromatoses are a set of inherited disorders designated as neurofibromatosis type 1 (NF1), neurofibromatosis type 2 (NF2), and schwannomatosis." (PMID 20418991, 2010). "Probably the most responsible for the prolonged misclassification of NF1 and NF2-SWN together was none other than Harvey Cushing who in 1917 stated that bilateral ‘nervus acusticus’ (VS) tumours were part of von Recklinghausen disease." (PMID 41160189, 2025). "However, following the elegant delineation of type 1 neurofibromatosis (NF1) by von Recklinghausen (1882), publications of NF2-SWN patients around the turn of the twentieth century were conflated with von Recklinghausen’s disease (NF1)." (PMID 41160189, 2025). "The patient reported no family history of neurofibromatosis type 1 or 2 (NF1/NF2)." (PMID 41179672, 2025). "Interestingly, the absence of a family history of neurofibromatosis type 2 (NF2) in this case contrasts with several previously reported cases, where intracerebellar schwannomas were associated with this genetic condition." (PMID 39444783, 2024).
neurofibroma (40 papers, 2012 to 2026). An intraneural or extraneural neoplasm arising from nerve tissues and neural sheaths. "Neurofibromas, typically associated with familiar NF1 and NF2, are well-understood, benign, peripheral nerve sheath tumors." (PMID 39070511, 2024). "The pathology demonstrated a mixed schwannoma-neurofibroma, and sequencing identified a SMARCB1 mutation with wild-type NF2 gene." (PMID 38058737, 2023). "Additional recurrent but low-frequency mutations in neurofibromas include FANCA, PTPRD, NF2, LZTR1, KNL1 and RUNX1." (PMID 37164978, 2023). "Tumors that occur in PMS typically include rhabdoid tumors, as in our index patient and neurofibromas involving the NF2 gene in patients with PMS and ring chromosome." (PMID 36899955, 2023). "Neurofibromas are divided into two subtypes, NF1 and NF2, of which NF1 is caused by mutations in the NF1 gene, is an autosomal dominant disorder that can affect many systems and is the most common neurofibroma." (PMID 33673851, 2021). "While multiple neurofibromas are commonly associated with hereditary syndromes like NF1 and NF2, isolated neurofibromas exist but are not well-described in the literature." (PMID 39070511, 2024). "Intriguingly, isolated colonic neurofibromas that are not linked with NF1 or NF2 are extremely rare." (PMID 39070511, 2024). "The hybrid-neurofibroma was found in a NF2 patient, the third ganglioneuroma in a child with NF1." (PMID 32506255, 2020). "Selumetinib is an MEK pathway inhibitor that has been FDA approved for plexiform neurofibromas in patients with neurofibromatosis type I.10,11 To the best of our knowledge, there is no published literature for the use of selumetinib for treating tumors in patients with NF2." (PMID 38058737, 2023). "Although neurofibromas predominate in NF1, concepts from NF2 studies can be considered for DRG enlargement in NF1." (PMID 40437318, 2025). "CRISPRi suppression of NF2 in NF1-mutant NF95.11b neurofibroma cells induced PAK1 phosphorylation (pPAK1) without significantly affecting pMEK, pERK, or pAKT compared to sgNTC." (PMID 38216572, 2024). "While none of our patients suffered from a known NF2, 4/33 patients (12,1%) had a known NF1: in the case of 2 neurofibromas and 2 MPNSTs." (PMID 39434082, 2024).